TNF (tumor necrosis factor)
Diseases named in the same sentence as TNF in open-access papers (continued):
Sharing a sentence is not in itself a finding about the gene and the disease.
infection (continued). "For assessing the cytokine response, negative correlations were observed (Spearman test) between pre-infection levels of pro-inflammatory cytokines (IL-1β, TNF-α, IL-6) and viral loads in the moment of sacrifice in multiple organs, including the brain, lungs, and heart." (PMID 40969767, 2025). "Minor changes on TNF expression were observed at 48 h after infection." (PMID 41139159, 2025). "Collectively, these findings suggest that conventional DMARDs, particularly MTX, appear relatively safe with respect to spinal fusion, while biologic DMARDs, especially TNF-alpha inhibitors, may increase perioperative risks, particularly infection." (PMID 41306173, 2025). "However, at 24 h post-infection, the expression levels of TNF-α, IL-1β, and IL-6 were markedly reduced, while the secretion of the chemokine IL-8 continued to increase, and the anti-inflammatory cytokine IL-10 was significantly upregulated (P < 0.05)." (PMID 40874199, 2025). "TNF-α being an early immune response activator may explain why the difference was more significant at 3 h post-infection than at 24 h in all experiments where a rise in TNF-α levels was observed." (PMID 40818988, 2025). "The levels of IL-6 and TNF-α in the supernatant and those of cellular proteins in Beas-2b cells infected with MP increased in a manner dependent on both the multiplicity of infection (MOI) and time." (PMID 41156647, 2025). "Infection with MHV-68 resulted in an elevated abundance of cytokines (TNF-α and IL-6) that triggered inflammation, an upsurge in pyroptosis-related molecules involving caspase-1, IL-1β, and IL-18, along with a decrease in IL-10 concentration, an anti-inflammatory cytokine, in peritoneal macrophages." (PMID 40041420, 2025). "In response to neuronal injury, infection, or stress, microglia become activated and secrete various pro-inflammatory molecules such as tumor necrosis factor (TNF)-α, interleukin (IL)-1β, IL-6, nitric oxide (NO), reactive oxygen species (ROS), and prostaglandin E2 (PGE2)." (PMID 40872491, 2025). "Infection with A. veronii triggered immune responses in mice that were mediated by TNF-α and IL-1β." (PMID 39980697, 2025). "In addition, OROV infection led to the release of the pro-inflammatory cytokine tumor necrosis factor-alpha (TNF-α) and induced neurodegeneration, indicating that OROV triggers an inflammatory response and tissue damage." (PMID 40143366, 2025). "We investigated the effects of mPGES-1 inhibitors (MF63 and MK886) on the production of pro-inflammatory cytokines (TNF-α, IL-1β, and IL-6), the anti-inflammatory cytokine IL-10, and the chemokine IL-8 in macrophages infected with E. coli at a multiplicity of infection (MOI) of 5:1." (PMID 40666730, 2025). "Furthermore, we found distinct cytokine profiles among groups, especially the marked increase of TNF-α and IL-10 in infection-induced ALI and IL-1β in gastric aspiration." (PMID 39969856, 2025). "Furthermore, ΔsodA infection resulted in attenuated inflammatory responses, evidenced by lower expression of IL-1β, TNF-α, and NF-κB p65." (PMID 41030551, 2025). "Pre-incubation with either HCMV variant for 24 h or 72 h before infection with A. fumigatus significantly and time-dependently suppressed gene expression and secretion of key cytokines such as CXCL8, VEGFA, IL-1α, IL-1β, IFN-γ, and TNF-α." (PMID 40980889, 2025). "Additionally, cytokines released in response to infection, such as TNF, can bind to death receptors on the cell surface, such as the Fas receptor." (PMID 40333197, 2025). "Within a large group of pro-inflammatory molecules, TNF-α which is predominantly secreted during infection, may promote sperm phosphatidylserine translocation and subsequent cell death." (PMID 40844768, 2025). "The acute-phase cytokine TNF-α is generated in the early phases of infection." (PMID 40303387, 2025).
infection (continued). "Additionally, PRV-GXLB-2013 infection induced a highly significant upregulation in mRNA expressions of TNF-α, IL-1β, IL-6, NF-κB p65, RIP3, and MLKL (p < 0.01), alongside a pronounced downregulation of IκBα (p < 0.01), in both brain tissues and C8-D1A cells." (PMID 40732040, 2025). "In addition, in the serum of infected chickens, higher levels of IL-1β compared to mock group were detected from 1 dpi to 7 dpi, and higher levels of TNF-α compared to mock group were detected from 6 hour post-infection (hpi) to 7 dpi." (PMID 40067802, 2025). "Additionally, another study has shown that older children, compared to their younger counterparts at the same stage of infection, have reduced levels of pro-inflammatory cytokines like TNF-α, IL-2, and IL-6, as well as Th1-biased chemokines." (PMID 41194029, 2025). "Similarly, TNF-α was stable throughout the first 6 days of the study until spiking significantly higher very late during infection at 7 DPC." (PMID 41156603, 2025). "TNF-α is one of the first cytokines released in response to infection or injury." (PMID 40648019, 2025). "PTX3 is produced locally at the site of infection and inflammation by a variety of cell types including fibroblasts, endothelial cells, mononuclear phagocytes, and DCs in response to pro-inflammatory signals such as TNF-α, IL-1β, Toll-like receptor agonist." (PMID 40646589, 2025). "TNF-α is indispensable for adaptive immune responses as it is necessary for developing lymphoid organs and can activate lymphocytes, thus enhancing the secretion of antibodies and cytokines to eliminate infection." (PMID 40109962, 2025). "Additionally, delivering immunomodulating genes such as IFNγ or TNFα enhanced the effects of the infection." (PMID 40547518, 2025). "At 6 hours after infection, the changes were dominated by TNF signaling and response to hypoxia." (PMID 39836471, 2025). "Currently, it remains unknown which pro-survival genes impact cell death induction during infection with reovirus, TNF, or Bcl2 inhibitor treatment." (PMID 41042063, 2025). "Finally, TNFα overexpression was restricted to B cells and ILCs following subcutaneous infection, while intravenously infected animals remained inconspicuous." (PMID 40178612, 2025). "The expression of p72 in macrophages containing inclusion bodies, together with the isolation results from the LVI–HVI1 subgroup, indicates that the observed necrotic lesions are a direct consequence of Arm07 infection, mediated by the secretion of TNF‐α, IL‐1, and IL‐6." (PMID 41395245, 2025). "TNF-α is known to facilitate the infiltration of macrophages, dendritic cells, NK cells, and neutrophils into affected tissues to attempt to control and clear infections." (PMID 40338080, 2025). "Oviedo-Boyso and colleagues reported that IL-1β and TNFα, when added to bovine endothelial cells before infection with S. aureus, increase their ability to eliminate intracellular S. aureus and S. epidermidis, thus remarking the role of IL-1β and TNFα in the interaction." (PMID 41425551, 2025). "Nevertheless, its infection risk remains low, with no reports of severe opportunistic infections, offering a safety advantage over TNF-α inhibitors." (PMID 40520203, 2025). "Furthermore, the levels of CXCL1, IL-6, and TNF-α in the culture supernatants were increased by EV-A71 infection." (PMID 39679722, 2025). "In experimental CD, the potential role of inflammatory mediators in CNS commitment is supported by in vitro data showing that IFNγ and TNF fuel the infection of astrocytes by T. cruzi through a complex network involving serotonin and creating a NO- and glutamate-enriched milieu." (PMID 41237192, 2025). "GF infection with Fusobacterium nucleatum, Porphyromonas gingivalis, or Filifactor alocis in the presence of tumor necrosis factor (TNF) led to synergistic induction of cyclooxygenase-2 (COX-2), a key enzyme in the PGE2 synthesis pathway, as well as secretion of PGE2." (PMID 40178270, 2025).
infection (continued). "Similarly, Yptb WT infection induced higher TNFα secretion in mouse peritoneal macrophages (PMs), which was attenuated in cGas−/− and Sting−/− PMs." (PMID 40365777, 2025). "The absence of TLR2 and TLR4 results in impaired phagocytosis and reduced levels of TNF-α, IL-6, IL-10, and nitric oxide, which could promote a persistent infection." (PMID 41346968, 2025). "Diagnostic value of serum TNF-α, IL-6, and IFN-γ in assessing the severity of infection." (PMID 40677522, 2025). "The benefits manifest at multiple levels, including the immune cell composition (e.g., preservation of naïve T cells and normalization of CD4/CD8 ratio), the inflammatory milieu (reduced TNF-α and CRP), and functional outcomes (enhanced vaccine responsiveness and lower infection risk)." (PMID 41514897, 2025). "The results showed that the polyclonal antibody not only effectively reduced the adhesion rate of MP cells to A549 cells but also significantly inhibited the expression of the key inflammatory factors IL-6 and TNF-α in Beas-2b cells and in model mice after infection." (PMID 41156647, 2025). "This study suggests that TNFα in the starry flounder may also possess mechanisms to regulate its expression in specific tissues to respond effectively to infections." (PMID 40723580, 2025). "Some studies suggest that the infection risk associated with TNF inhibitors is comparable to that of non-biological DMARDs, while others highlight an increased risk of serious infections with TNF inhibitor treatment." (PMID 40018478, 2025). "Cytokine levels decreased for 6 of 9 assayed cytokines or the chemokine in the Chr7x3 AAB variant (IL-17a, IL-22, IL-5, IFN-γ, TNF-α, and IL-1β) and further decreased for all cytokines and the CXCL1 chemokine in the Chr7x3 ABB variant when compared to infection with Chr7x2 SC5314." (PMID 40577316, 2025). "As the infection progresses, macrophages and neutrophils migrate quickly to the site of infection, phagocytize pathogens, and release inflammatory cytokines (e.g., IL-1 and TNF-α) to amplify local defenses." (PMID 39861857, 2025). "Conversely, at 72 hours post-infection, the secretion of IL-6, IL-17, T-bet, TNF-α, and IFN-γ was significantly diminished (P < 0.01), while levels of TGF-β, GATA-3, IL-10, and IL-4 were significantly elevated in the Pm_OMVs-infected group compared to the Pm group (P < 0.01)." (PMID 41306977, 2025). "Infection and death of thymocytes and thymic stromal cells by HIV, infection of hematopoietic stem cells, accelerated thymic atrophy, effects of pro-inflammatory cytokines (TNF), and intense degree of activation are among the factors involved in the impaired thymic function." (PMID 40145085, 2025). "Additionally, these T cells potentiate IFNγ production by natural killer (NK) cells, via TNFα and interleukin (IL)-12 produced during infection." (PMID 41452934, 2025). "However, during severe infections, TNF and IL-1 interfere with both NREM and REM sleep, leading to sleep fragmentation." (PMID 39940855, 2025). "Given the inflamed lymphoid environment induced by infection, unexpectedly, the inflammatory cytokine TNF appears to inhibit the expansion of GC B cells, T‐bet+ plasmablasts, and T‐bet+ ABCs, because these populations underwent expansion following TNF ablation." (PMID 39844597, 2025). "E. faecalis can survive in dentinal tubules and resist the sodium hypochlorite irrigation in conventional root canal treatment while surviving within Mφ for up to 72 h, inducing the production of pro-inflammatory cytokines such as TNF-α and leading to the persistence of infection." (PMID 40572241, 2025). "Furthermore, infection with Mab has been shown to worsen during immunosuppressive therapy involving TNF-α inhibitors, further emphasizing the critical role of TNF-α in regulating the immune response to this pathogen." (PMID 41294882, 2025). "Conversely, the percentage of IL-1β+ and TNF+ microglia increased by day 6 post-infection." (PMID 40771825, 2025).
infection (continued). "In addition to the known finding that HAdVs utilize NF-κB during the early phase of infection for efficient replication, we demonstrate that TNFα-induced immune responses via the NF-κB pathway are repressed by E1B-55K during the late phase of replication." (PMID 40103806, 2025). "Additionally, cytokine analysis revealed that IL-6 and TNF-α levels were elevated in the infection group but significantly reduced in the APR treatment group within 24 h, emphasizing the immediate anti-inflammatory effects of APR." (PMID 40284856, 2025). "Abatacept is contraindicated in patients with active or chronic infections, such as tuberculosis or hepatitis B/C, and should not be combined with other biologic agents, especially TNF-α inhibitors, due to increased infection risk." (PMID 40142915, 2025). "Constant activation of immune response through interleukin-6 (IL-6) and tumor necrosis factor-alpha (TNF-α) to recruit immune cells-such as leukocytes- to the site of infection can also impair vascular permeability and affect vascular pulsatility and astrocytic support function." (PMID 40502828, 2025). "During the early stages of infection, alveolar macrophages and dendritic cells play a pivotal role in pathogen recognition and the secretion of key cytokines, including interleukin-1β (IL-1β), tumor necrosis factor-α (TNF-α), and IL-6." (PMID 40006698, 2025). "Cytokine levels decreased for 6 of 9 assayed cytokines or the chemokine in the Chr7×3 AAB variant (IL-17a, IL-22, IL-5, IFN-γ, TNF-α, and IL-1β) and further decreased for all cytokines and the CXCL1 chemokine in the Chr7×3 ABB variant when compared to infection with Chr7×2 SC5314." (PMID 39896449, 2025). "Under mechanical injury, stress, or infection, the AF and NP secrete TNF-α and IL-1β." (PMID 40356987, 2025). "In the later stages of infection, elevated serum expression of TNF-α indicated the persistence and exacerbation of the systemic inflammatory response, suggesting that reducing serum TNF-α levels could potentially alleviate lung inflammation." (PMID 40475788, 2025). "The table below presents the mean values of the concentrations of the analyzed proinflammatory cytokines; TNF-α, IL-1β and IL-6 (expressed in picograms per milliliter [pg/mL]) ± standard deviation measured in patients with PCOS with infections caused by atypical pathogens and in the control groups." (PMID 40647668, 2025). "In contrast, only IL-10 and TNF-α were reported in a study of natural infections in Africa." (PMID 40743218, 2025). "The favorable outcomes observed in the present study can be explained as Losartan-only and Losartan + Lisinopril combination treatments resulted in marked reductions in the levels of the pro-inflammatory cytokines IL-6 and TNF-α following infection by SARS-CoV-2." (PMID 40868984, 2025). "Thus, tissue-resident and infection-induced lung IMs control lung viral loads, at least in part by secreting TNF, which can be suppressed by ACh." (PMID 40263611, 2025). "Furthermore, analysis of serum inflammatory cytokines indicated that montelukast effectively suppressed the secretion of pro-inflammatory mediators such as TNF-α and IL-6, suggesting a dual role in infection control and inflammation modulation." (PMID 41090944, 2025). "Intriguingly, we speculate that the inflammatory response elicited by the parasite also has a central role in this process, as TNF is an important regulator of host energy metabolism and promotes hypoglycaemia during acute infection with P. chabaudi." (PMID 39842477, 2025). "Although infection with two invasive NTHi strains did not cause noticeable differences in ICAM-1 or TNF-α expression, NTHi 08-252 induced higher IL-1β release." (PMID 40137696, 2025). "Infection of neutrophils and Ly6C+ monocytic cells with STm in vitro also induced TNF." (PMID 40064845, 2025).
infection (continued). "The activation of NF-κB in macrophages initiates an inflammatory cascade and promotes their recruitment to sites of infection, where activated M1 macrophages secrete TNF-α, IL-1β, IL-6, and other cytokines to mobilize neutrophils and initiate the host response." (PMID 41347221, 2025). "Hence, our data suggests that blocking K48-dependent polyubiquitination tempers the production and release of TNF at the basal level prior to any MNoV_S99 infection." (PMID 40395509, 2025). "The levels of pro-inflammatory cytokines, such as tumor necrosis factor alpha (TNF-α), interleukin 6 (IL-6), and interleukin 1 beta (IL-1β), which drive chronic inflammation in plasma and lymph nodes, remain elevated from early infection stages and persist even in ART-treated individuals." (PMID 40704918, 2025). "Additionally, quantification of the levels of IL-1β, IL-6, and TNF-α pro-inflammatory cytokines showed that old murine BMMs displayed similar levels of IL-1β, IL-6, and TNF-α 24 h after infection with Aa or Pg compared with controls in young BMMs." (PMID 40649955, 2025). "In addition, in vitro studies using a human blood-brain barrier (BBB) model showed that USUV infection leads to upregulation and release of inflammatory cytokines such as IL-6, TNF-α, and IL-1β, both on the apical and basolateral sides of the barrier." (PMID 40731345, 2025). "Similarly, TNF-α exhibits dual functions in the TMEV infection model, likely depending on the disease phase and expression level." (PMID 41214106, 2025). "Although an increase in TNF-α production has been observed in reproductive tissues, especially in the first week of infection, levels may also gradually decrease during infection." (PMID 40647668, 2025). "For infection severity diagnosis, ROC curve analysis demonstrated that serum TNF-α, IL-6, and IFN-γ levels had diagnostic value in assessing DFI infection severity, with AUC values of 0.811(95%CI: 0.734-0.927), 0.793(95%CI: 0.705-0.857), and 0.764(95%CI: 0.699-0.839), respectively." (PMID 40677522, 2025). "Strikingly, TNF levels measured in cecum tissue were significantly elevated in S. TmWT-infected mice compared to those infected with S. TmSPI2, consistent with earlier studies proposing TNF as a key mediator of epithelial barrier disruption during S. TmWT infection." (PMID 41370284, 2025). "Similarly, high TNF-α expression levels in the hamster were observed from 1 to 22 h post-infection, returning to baseline levels from 24 h post-infection." (PMID 40732660, 2025). "TNF-α is one of the agents whose concentration increases in such situations, and one of its roles is the stimulation of cytotoxic activity of monocytes and macrophages as a response to, i.a., infection." (PMID 40509141, 2025). "Furthermore, the apoptosis inhibitory protein (IAP) family members ORF87 and ORF106 have been shown to maximize the amplification of viral particles in the early stages of infection by inhibiting TNF-mediated cell apoptosis in Pacific oyster cells." (PMID 40007037, 2025). "infection in the gallbladder triggers an intense inflammatory response, manifested by elevated levels (more than 10-fold) of proinflammatory mediators such as tumor necrosis factor-α (TNF-α), interleukin-6 (IL-6) and monocyte chemotactic protein-1 (MCP1)." (PMID 38774627, 2024). "Indeed, activated dendritic cells, macrophages, and NK cells target the site of infection and secrete IL-1β, IL-6, and TNF-α, while activated CD4+ T and CD8+ T cells produce IFN-γ among other inflammatory cytokines that aggravate tissue damage." (PMID 38911850, 2024). "However, it is known that infection-induced alterations in sleep is a CNS response to IL-1 and TNF-α." (PMID 39066248, 2024). "Additionally, the levels of the pro-inflammatory cytokines IL-1β, IL-6, and TNF-α in serum samples collected from infected chickens at 24 h post-infection were detected." (PMID 39596124, 2024).